LINC01491 (long independently transcribed non-coding RNA 1491)
Gene: Long non-coding RNA gene on chromosome 15 (47,774,219 to 47,847,155, reverse strand). Ensembl gene ENSG00000259572.
Diseases named in the same sentence as LINC01491 in open-access papers:
LINC01491 is named in the same sentence as 2 diseases in open-access papers, as found by Europe PMC text mining. Sharing a sentence is not in itself a finding about the gene and the disease.
LINC01491 shares sentences with these, for which no sentence is quoted: primary pulmonary hypertension (1 paper); pulmonary arterial hypertension (1).